RB1 (RB transcriptional corepressor 1)
Diseases named in the same sentence as RB1 in open-access papers (continued):
Sharing a sentence is not in itself a finding about the gene and the disease.
tumor (continued). "It has been shown that ESRP1/2 activation leads to oncogenic activation of several ESRP1/2 target genes such as MAP 3 K7, mTOR, GSK3ß, RB1, CTNND1, E-Cadherin, and CD44, which drive tumor cell proliferation and EMT, key features of advanced and aggressive cancers." (PMID 33339518, 2020). "Since Rb1/p107/Hells TKO mice develop tumors at a reduced frequency and with slower progression rates than Rb1/p107 DKO mice, we aimed to identify pathways regulated by HELLS that aid in the delayed tumor progression." (PMID 32071286, 2020). "No alterations of the RB1 sequence were detected in tumor or blood DNA samples, consistent with the results of Sanger sequencing and multiplex ligation-dependent probe amplification (MLPA; not shown)." (PMID 33270844, 2020). "Moreover, LD plot showed strong LD between exonic RB1 SNP (rs121913300) and intergenic CCND1 SNP (rs614367) in tumor patients." (PMID 32373934, 2020). "Chimæra analysis suggested that the RB1 locus deletion predates the PTEN mutation and that the BRCA2 and EP300 mutations were acquired in tumor subclones that following RB1 loss, lacked the PTEN mutation." (PMID 32843649, 2020). "However, recent evidences put pRb at the crossroads of multiple pathways, in a context-dependent manner, where intact RB1 is often integral to promoting tumor initiation and progression." (PMID 33396222, 2020). "RB1 is a negative cell cycle regulator involved in the G1/S cell cycle checkpoint and was the first tumor-suppressor gene identified as dysfunctional in several major cancers." (PMID 31028247, 2019). "The rb1/rb1 mutant transcriptome was used for comparative analysis with the tumor transcriptome to identify molecular pathways that distinguish transformed rb1 tumor cells from nontransformed rb1/rb1 mutant cells." (PMID 29914980, 2018). "For example, our core mRNA signature included tumor-suppressor genes CDK6 and RB1." (PMID 30404194, 2018). "It should be noted that deletions of the CDKN2A/B and RB1 suppressor genes are present in T-ALL (70% and 12%, respectively) and B-ALL (36% and 8%, respectively) in which they contribute to the disruption of the tumor suppressor pathways in ALL." (PMID 29642462, 2018).
tumor (continued). "RB1, which is regulated by CDK4, showed a significantly lower expression in CDKN2Ahigh (p < 0.001) and the downstream transcription factor gene E2F3 was significantly higher expressed in CDKN2Ahigh tumours (p < 0.001)." (PMID 30258198, 2018). "It was notable that cdkn2a/b and rb1 double somatic inactivation did not influence the overall tumor incidence rate, and merely lead to form the mixture of MPNSTs & MB-like PNETs in an each single tumor developing zebrafish." (PMID 28903419, 2017). "Among the putative target mRNAs, they could specify known tumor genes, such as RB1 (Retinoblastoma 1, tumor suppressor) and TGFBR2 (transforming growth factor, oncogene)." (PMID 28793339, 2017). "Additionally, in vivo abemaciclib leads to a substantial reduction in tumor volume through downregulation of CDK4, CDK6, Cyclin D, Rb1, and E2F1 gene expression." (PMID 29245989, 2017). "In conclusion, the epigenetic interaction between Linc00441 and bidirectional transcripted neighbor RB1 may be a de novo theory cutting-point for the inactivation of RB1 in HCC and may serve as targeting site for tumor therapy in the future." (PMID 28300839, 2017). "Together these studies directly demonstrate that p16 has tumor suppressive functions that are not mediated through RB1 and are critical for protecting against carcinogenesis." (PMID 28414317, 2017). "The current paradigm is that p16 and RB1 function in a linear pathway to suppress tumorigenesis; however p16 is preferentially lost in human cancers suggesting that p16 has critical tumor suppressive functions not mediated through RB1." (PMID 28414317, 2017). "BRG1 loss is not yet recognized as a major mechanism of RB1 pathway inactivation, in part because BRG1 loss occurs concomitantly with tumor cell loss of CDKN2A (p16) or RB1." (PMID 28105458, 2016). "For one tumor (T16), indeed no second RB1 hit or MYCN amplification was found by conventional DNA diagnostics (true negative)." (PMID 27126562, 2016). "In contrast, in the primary tumor RB1 expression was heterogeneous with most parts lacking RB1 entirely while some minor areas demonstrated RB1 expression in a subset of tumor cells." (PMID 27121059, 2016). "We compared the percentage of Pcna immunoreactivity in WT tumor cells that expressed pRb1Hyper (inactive Rb1) and those that did not (i.e., expressed pRb1hypo)." (PMID 28105458, 2016). "These include RB1 and EGFR, the top-scoring tumor suppressor and oncogene, respectively." (PMID 27321817, 2016). "In our study, the genes CDKN2B, CDKN2A, and RB1 were not methylated and hipoexpressed in all the tumor grades analyzed." (PMID 26317630, 2015). "Among the genes that are mutated between 5 to 20% in TCGA GBM tumor samples, we found mutations in NF1, SPTA1, TCHH and ATRX genes, although, the other genes like PIK3R1, PIK3CA, RB1, IDH1 and KEL were not mutated in any cell line." (PMID 26496030, 2015). "There is a negative correlation between Rb1 and P16 (r = −0.12) and Rb1 and tumor grades (r = −0.2)." (PMID 26043844, 2015). "Also, in hematopoietic progenitors from DBA patients, some members of the RAS family are upregulated, whereas the tumor suppressors breast cancer 2, early onset (BRCA2) and retinoblastoma 1 (RB1) are downregulated." (PMID 26398160, 2015).
tumor (continued). "Interestingly, tumor suppressors PTEN and RB1 co-occurred in our extension dataset (P = 0.019), harboring six and four truncation events, respectively." (PMID 25393105, 2014). "While neither cases 19 or 20 had clinical evidence of MDS, both cases 18 and 19 showed widespread copy number changes in the peripheral blood–including the RB1 locus in case 19–suggestive of somatic tumor changes rather than germline events." (PMID 23894400, 2013). "The complete penetrance of tumor formation, growth and progression results in a short lifespan for Rb1+/− mice, which, unlike wild type mice, is minimally affected by diet restriction." (PMID 23454836, 2013). "Tumor DNA was analyzed for alterations in selected genetic loci (1p36, 9p22, 10q23–24, 17p13, 19q13, 22q12), isocitrate dehydrogenase 1 (IDH1), isocitrate dehydrogenase 2 (IDH2) and the CpG island methylation status of critical tumor-related genes (MGMT, P16, DAPK, PTEN, RASSF1A, Rb1)." (PMID 23826216, 2013). "Of these, 6 out of 9 samples received negative P-Shifts consistent with RB1's characterized role as a tumor suppressor." (PMID 22962493, 2012). "In order to utilize anti-tumor agents whose effect is different between RB1-positive and -negative cancers, the development of a predictive biomarker that discriminates the status of RB1 in cells is essential." (PMID 21447152, 2011). "Development of anti-tumor agents which selectively kill RB1-negative tumors is expected to increase the therapeutic window for treatment of tumors with an RB1-negative background." (PMID 21447152, 2011). "Many researchers are attempting to develop anti-tumor agents that are preferentially effective against RB1-negative tumors." (PMID 21447152, 2011). "In the absence of normal RB1, genomic instability and chromosomal aberrations accumulate, leading to tumor initiation, progression, and ultimately metastasis." (PMID 20664703, 2010). "Tumor samples were not available for analysis, a reason why studies of RB1 expression were not carried out with this material." (PMID 19640284, 2009). "The highest frequency of RB1 LOH was observed in tumours of the basal-like (13 of 18, 72.2%) and luminal B subtypes (8 of 13, 61.5%), both of which are known to be highly proliferative tumour subtypes." (PMID 18782450, 2008). "Indeed chromosome 13 harbors tumour suppressor genes such as BRCA2 (13q12.3) and retinoblastoma gene (RB1) (13q14)." (PMID 17908304, 2007). "Our findings suggest that patients with well-sampled tumours fulfilling the WHO criteria for AA having genetic abnormalities affecting any of the genes coding for the components of the Rb1 pathway have a poor outcome." (PMID 15970925, 2005).
tumor (continued). "No expression of RB1 was found in tumor tissue by immunohistochemistry evaluation." (PMID 40463882, 2025). "For example, although 72 (61.5%) mutations, including an oncogenic RB1 S249* mutation, were shared between the SMBO-109 PDO and the tumor from which it was derived, ERBB2 amplification was present only in the organoid line but not in the tumor." (PMID 41422272, 2025). "However, there are certain requirements for inclusion in clinical patients, for example, tumor tissue samples should have increased protein expression of KLF5, XPO1 and Cyclin D1, and no mutation of RB1 and positive expression in the cytoplasm." (PMID 39888288, 2025). "Only in one tumor we found an additional pathogenic variant with our NGS panel, which was a truncating BCOR mutation (R1472 frameshift-deletion; VAF of 80%) in a PB-RB1 tumor with a homozygous RB1 deletion (not shown)." (PMID 41291966, 2025). "In addition, we found that RB1 and PTEN tumour suppressors remained intact in all clones." (PMID 39237765, 2024). "Scientists postulate that RB1 loss is a prototypical oncogenic change that promotes OXPHOS, that aggressive tumors acquire lethal combinations of oncogenes and tumor suppressors that stimulate anabolism as opposed to OXPHOS, and that targeting both metabolic pathways would be therapeutic." (PMID 37322261, 2024). "In RB1 proficient tumours with elevated E2F expression, it may not be sufficient to target Cdk4/6 with Palbociclib but also target the E2fs." (PMID 37606819, 2024). "However, previous tumor studies of RB1 expression have not also defined the HRD status of individual samples." (PMID 38837893, 2024). "The risk depends on the failure to identify all germline mutations and the possibility of gonadal mosaicism in parents, both of which can be excluded if two somatic hits in RB1 are identified in tumor DNA and not in blood, thus leaving siblings with population risk only." (PMID 38803632, 2024). "However, several notable tumor suppressors of modest size, including BRCA1, NF1, and RB1, could be phased completely in only around half of tumors, suggesting other locus-related features may reduce their phasing potential." (PMID 39406235, 2024).
tumor (continued). "NGS analyses revealed that the CN of BRCA2 and RB1 in adjacent normal prostate tissues was not decreased in 10 patients with PC with tumor BRCA2 alteration, suggesting that in the present study, BRCA2 and/or RB1 deletions were caused by somatic gene alterations." (PMID 36645189, 2023). "In addition, there has been emerging evidence of non-canonical roles of RB1 in tumor metabolism, the tumor microenvironment, and epigenetics; these pathways remain poorly understood, and the clinical implications are yet to be determined." (PMID 37046760, 2023). "Patients with both RB1 loss and germline BRCA mutations had a superior OS (HR 0.38, 95% CI 0.25-0.58, P = 5.2 ×10-6) compared to patients with either alteration alone, and their median OS was three times longer than non-carriers whose tumours retained RB1 expression (9.3 years vs. 3.1 years)." (PMID 37986741, 2023). "However, the role of Rb1 in modulating intrinsic tumor immunogenicity has not been thoroughly addressed." (PMID 35267571, 2022). "Retinoblastoma‐1 (RB‐1) is a tumour‐suppressor gene, which is negative in SAF." (PMID 36092267, 2022). "We found that miR‐192‐5p/RB1 is correlated with Tregs but not Th17 cells in tumour tissues." (PMID 35969010, 2022). "Interestingly, KO of JAK–STAT genes in wild-type sgNT cells or in sgTP53/RB1-KO cells treated with vehicle did not influence tumor cell survival, suggesting a specific role of JAK–STAT signaling in lineage plasticity-driven AR therapy resistance." (PMID 36065066, 2022). "Knockdown of RB1 cannot completely restore tumor growth nor restore autophagy." (PMID 36230664, 2022). "Consequently, Rg3-Rb1 NPs afforded superior inhibition of tumor growth and reduction of pulmonary metastasis than the Rg3 and Rb1 mixture, with no obvious systematic toxicity in vivo." (PMID 36032706, 2022). "Interestingly, combination of CDK-i and autophagy-inhibitors was also effective in other tumor cell lines, if RB1 was intact and no oncogenic form of cyclin E was present." (PMID 35712501, 2022). "Altogether, the livers and spleens of the tumor-bearing mice were larger than those of the normal mice, yet WEG cannot ameliorate the weight reduction of the liver and spleen; however, GE5, GE50, and Rb1 can help the liver weights of the cancer cachexia mice return to normal." (PMID 32020864, 2020). "Loss in FHIT and RB1 were the only well described HNSCC associated mutations detected in TADE and which were absent from both the tumor and NE, suggesting this TADE is an independent clone and not related to the tumor." (PMID 32426287, 2020). "However, there is increasing evidence that RB1 has a number of non-canonical tumor suppressor functions including regulating DNA damage responses, inducing senescence, activating apoptosis, and preventing aneuploidy/chromosomal instability." (PMID 32591511, 2020).